FOXP3 (forkhead box P3)
Diseases named in the same sentence as FOXP3 in open-access papers (continued):
Sharing a sentence is not in itself a finding about the gene and the disease.
tumor (continued). "In the spleens of tumor-bearing mice, we observed significantly elevated CD38+ cells in FoxP3 negative CD4+ T cells." (PMID 36757800, 2023). "IHC staining results indicated that the deletion of ALKBH5 significantly increased the number of tumor-infiltrating CD3+, CD4+, and CD8+ T cells but not in the FOXP3+ cells." (PMID 36566230, 2022). "In the tumour drainage lymph nodes (TDLNs) of the combination group, there was a 18% reduction in CD8+IFN‐γ+ T cells and a 0.47% reduction in CD4+CD25+FOXP3+ regulatory T cells, as opposed to 5.0% and 5.1% reductions, respectively, for the control group." (PMID 35174623, 2022). "Our study found that sTILS, CD45+, CD3+, CD4+, and CD8+ cells tended to have a higher frequency in tumor tissue (stromal) and that the frequencies of CD20+, FoxP3+ and CD68+ cells in tumor tissue did not change after-NAT compared with before-NAT." (PMID 35562400, 2022). "Despite the fact that UA-liposomes are only able to slow down tumor growth without completely destroying tumor tissue, an in vivo administration of these liposomes led to a depletion of MDSCs and CD4+CD25+Foxp3+ Tregs in the TME." (PMID 35335881, 2022). "We have furthermore shown that high levels of tumor CD3(+), CD68(+) cells and TIL FoxP3 predict better twenty-year OS, both overall and among non-OPSCC-related deaths." (PMID 36289746, 2022). "Many different types of lymphocytes have been identified in the TME (CD4+ with/without suppressor FoxP3+ expression, CD8+ with/without PD-L1 expression, and M2 macrophages), reflecting the complex interplay between tumor antigenicity and host immune reaction." (PMID 35158822, 2022). "TME composition at relapse significantly associated with an increase of CTLA4 gene counts normalized to tumor-infiltrating CD3 gene counts but not of FoxP3 gene." (PMID 36038629, 2022). "Fifth, our study only confirmed the relationship between YTHDF1, YTHDF2, CD4, CD8, and FOXP3, however did not reveal which pathway YTHDF1, YTHDF2 affects on the tumor immune profile." (PMID 36479088, 2022). "Only the percentage of intratumoral CD8+ Teffs (CD8+CD25+) and CD4+ Teffs in the tumor and drained lymph nodes (CD25+FoxP3−), but not that of the circulating Teffs, was significantly decreased." (PMID 35955841, 2022). "We found that besides TNFRSF4, Treg functional signature genes such as FoxP3, CTLA4, TIGIT, TNFRSF18 (GIRT), CCR8, LAYN, and MAGEH1 were also overexpressed in C11-Tregs-FoxP3 of treatment-naive and non-MPR tumor lesions, but not for MPR tumor lesions." (PMID 35831283, 2022). "For IHC, although not correlated, the ratio of FoxP3+ to CD8+ cells was 0.39 fold intratumorally and 0.59 fold at the tumor borders, suggesting that the prognostic effect was indeed due to the presence cytotoxic T cells." (PMID 36268020, 2022). "Based on the frequency of non-suppressive Fr-III FoxP3+ T cells, they subdivided CRC into type A and B tumours." (PMID 35140715, 2022). "Of the 7 paired biopsies that were collected, 3 did not have sufficient tumor tissue for analysis (in the pre- and/or post-treatment biopsies), and 4 were evaluable for CD8 and FOXP3 IHC staining." (PMID 34257408, 2022). "Conversely, a strong positive correlation (r = 0.783, p < 0.0001) was observed between levels of FoxP3+ Tregs and CD4+TIM-3+ T cells in tumor tissues but not in normal tissues." (PMID 35455287, 2022). "A previous study found that IRF1 was found to negatively regulate the function of CD4+CD25+ Treg cells by directly and specifically repressing the expression of FOXP3 gene, suggesting the negative correlation between IRF1 and FOXP3 in tumor immunity." (PMID 35664436, 2022). "If the patients were stratified by tumor median CD3 levels, the five-year DSS survival prediction by Foxp3 TIL levels were still valid (p = 0.007) (Results not shown)." (PMID 35326661, 2022).
tumor (continued). "Immunohistochemically assessed tumor PD-L1 expression was scored as: negative, low, intermediate or high, while CD8+ and FOXP3+ staining were automatically quantified and the mean values were statistically analyzed." (PMID 35875133, 2022). "Compared to tumor from WT group, the HDAC2-KO group had a higher percentage of CD45+ lymphocytes, CD3+, and CD8+ T cells, but not CD4+ population or CD4+FOXP3+ Treg cells." (PMID 34365463, 2021). "Neither the number of CD8, FOXP3, nor CD27-positive TIL showed difference between CD70-high and low tumor, whereas the number of FOXP3-positive iTIL in CD70-high TSCC was slightly higher than CD70-low (p = 0.07)." (PMID 35145909, 2021). "Strikingly, while intratumoral Treg abundance based on FOXP3 mRNA expression did not correlate with clinical features, stratifying patients based on the CCR8:FOXP3 ratio in the tumor revealed a strong correlation with poor survival in patients." (PMID 34632244, 2021). "Although we observed a decrease in FOXP3+Tregs at stage III, we noted that their values still remained increased in the periphery irrespective of tumor stage." (PMID 34502204, 2021). "Reportage of tumor RORC-Treg infiltration was calculated from the averaged, normalized levels of FOXP3, CTLA4, GITR, RORC and GATA3." (PMID 34681642, 2021). "While the CD3+ and CD8+ tumor infiltrate was increased in the RGS-treated tumors, there was no significant alteration in the level of CD4+FoxP3+ T regulatory cells (Tregs) or angiogenesis (CD31)." (PMID 34092233, 2021). "When we transplanted 1 million CD8+ T cells from WT mice and treated with 0.5 million CD25+FOXP3+ Tregs from WT mice, recipient mice were not protected from developing GVHD, although they cleared tumour cells." (PMID 34919342, 2021). "Altogether, these data support a role for tumor-infiltrating CD30+OX40+, but not CD30−OX40+ or CD30+OX40−, Foxp3+ Tregs in predicting OS of CRC patients." (PMID 33527196, 2021). "In spleens of tumor-bearing mice, chemotherapy down-regulated CD4+ TNFR2+ FOXP3+ cells but the subset of CD8+ TNFR2+ PD-1+ was not present prior to chemotherapy and was not increased by the treatment." (PMID 34201054, 2021). "Our results show that PD-L1 positive tumor biopsies had significantly more CD8+ (cytotoxic T-cells), CD20+ (B-cells), and FoxP3+ (Tregs) cells than PD-L1 negative tumors." (PMID 34445631, 2021). "In contrast to the DCs treated with control tumor lysate, which increased the proportion of conventional FoxP3+ CD4 Tregs, the PAM-treated tumor lysate did not potentiate the Treg-inducing capacity of DCs." (PMID 33915703, 2021). "Moreover, the percentage of Treg (CD4+, CD25+, FoxP3+), which is associated with a poor prognosis, was not altered by KLS-3010, while effector T cells (Teff; CD8+ IFF-γ+, and CD4+ IFF-γ+) were significantly increased among tumor-infiltrating lymphocytes in KLS-3010-treated mice." (PMID 32854548, 2021). "Analysis of the tumor microenvironment by flow cytometry revealed that the primary tumor showed a higher frequency of CD3+ and CD8+ cells, while the proportion of CD4+Foxp3+ cells was not different from the recurrent tumor." (PMID 34221953, 2021). "PtenΔ/ΔBRF1Tg tumours contained significantly fewer stromal CD3 and CD4 T cells (p = 0.0438, 0.0394, respectively) but stromal CD8 or FOXP3 (a marker for regulatory T cells) T cells were not altered." (PMID 31740786, 2020). "No Foxp3+ MAIT cells were detected in the PBMCs of these patients, and only a few were observed in adjacent non-tumor tissue samples." (PMID 33205061, 2020). "By contrast, in the tumour nests the CD8+ and FoxP3+ lymphocytes, and not the CD4+ and CD20+ cells, were significantly associated with survival, and only in the ER/PR positive patients." (PMID 32577938, 2020). "We discovered that YAP plays a role in non-Treg T cells through tumor studies of the YAP fl/fl CD4 Cre and YAP FoxP3 YFP Cre animals (T cell and Treg-specific deletion of YAP)." (PMID 32322254, 2020).
tumor (continued). "Tr1 lymphocytes have been detected in both tumor tissue and peripheral blood of EBV+ cHL patients, and configure a regulatory subset lacking Foxp3, but usually expressing integrin subunit alpha 2 (ITGA2) and lymphocyte-activation gene 3 (LAG3)." (PMID 33327433, 2020). "Although the tumor Treg proportion was not increased due to the infection in the PLN from infected mice, we detected a higher proportion of CD4+/Foxp3+ Treg cells in the PLNs of both T. canis-infected mice and the 4T1+T." (PMID 32547942, 2020). "In this work, we show an increased CD4+FOXP3+ T cell density in the tumour core correlated with prolonged survival and CD4+FOXP3+ T cells clustered with CD8+ T cells rather than tumour cells." (PMID 32377339, 2020). "There was no statistical difference in the densities of CD4+FOXP3+ T cells, DNT cells, CD56+ cells and lineage− cells between the tumor core and edge." (PMID 32377339, 2020). "Using the novel ISAT algorithm, we observed that a high number of CD4+FOXP3+ T cells interacting closely with CD8+ T cells, but not the tumor cells." (PMID 32377339, 2020). "Recent studies have demonstrated that tumor-derived Th17 cells produce low levels of TGF-β and IL-10 after stimulation with anti-CD3 in vitro and express CTLA4, FoxP3, and CD25 as Treg cell markers, while they do not suppress tumor progression." (PMID 31024835, 2019). "A higher number of tumor-infiltrating FoxP3+ Treg in primary PTC and metastatic lymph nodes tissues was present, and no FoxP3 expression in the MNG tissues was found." (PMID 31500315, 2019). "We found that HMGB1, secreted from tumor cells treated with DOC-based chemotherapy, did not influence the presence of suppressive myeloid (CD33+/CD11b+ MDSC) or Foxp3+Treg cells in tumors." (PMID 30744691, 2019). "In patients with primary UM, while circulating anti-tumor CD3–CD56dim NK cells and CD8+ and double-negative CD3+CD56+ NK-T cells decrease, pro-tumoral ICOS+CD4+FoxP3+ Treg cells increase, further supporting a role for Treg in tumor progression." (PMID 31750244, 2019). "In the current study, the high density of CD4+ T cells and Foxp3+ Treg cells, but not CD8+ T cells, in the tumor microenvironment was positively correlated with better PFS." (PMID 30978241, 2019). "Mice without STAT3 in myeloid compartment of tumor stroma, including DCs and macrophages, present reduced numbers of tumor-infiltrating CD4+CD25+/FOXP3+/LAG3+ Tregs, along with an increase in CD8+ effector T-cells." (PMID 31480382, 2019). "Other leukocytes, such as CD4 T cells, Foxp3+ Tregs, CD8 T cells, and dendritic cells, in the tumor stroma were not affected by MEL or MEL-dKLA treatment." (PMID 31174610, 2019). "Surprisingly, helper/regulatory CD4+ T cells (CD4+, CD45+), known to promote tumor growth, were unchanged, and additional flow cytometry analysis by CD25 and FOXP3 staining showed no change in regulatory T cells." (PMID 30458886, 2018). "While PD-L1 expression was slightly but significantly increased within the tumor core, we noted that neoadjuvant (NA) chemotherapy did not impact NKp46, CD163 and Foxp3 infiltrate." (PMID 30454021, 2018). "Despite the decreased-percentage of PD1 positive cells and Foxp3 positive cells in CD4+ and CD8+ T cells following treatment with EP1 or EP2 without pIL-12, tumor growth continued in EP1 and EP2 groups." (PMID 30544810, 2018). "Curiously, the tumor protection induced by metformin was not altered when CD25+ cells were depleted, suggesting that CD4+Foxp3+IL-10+ T cells induced by metformin treatment do not impair the observed antitumor effect." (PMID 29899823, 2018). "In contrast, blockade of ICOSL during T cell activation reduced Foxp3 expression but did not eliminate it, indicating that there are some other factor influencing Foxp3 expression, such as TCR signals and perhaps other tumor factors." (PMID 30319662, 2018).
tumor (continued). "They found that tumor-infiltrating CD4+ T cells were skewed toward Treg (FoxP3+, forkhead box P3) and T helper 17 (Th17) phenotypes rather than Th2 phenotype." (PMID 28292326, 2017). "Although depletion of NK cells did not alter the proportion of Foxp3+CD4+ T cells within B16SLC35A1 tumors, the CTL/Treg ratio was only in favor of tumor control in NK replete B16SLC35A1." (PMID 26741508, 2016). "An inflammatory environment, not infrequent in tumours, can induce the transformation of FOXP3+ Tregs into FOXP3− effector cells producing IFN-Υ." (PMID 27777963, 2016). "Irrespective of HPV status, all tumor samples were infiltrated by CD3+ T cells, which comprised a substantial population of CD3+FoxP3+ Tregs." (PMID 26899388, 2016). "As this late accumulation does not prevent tumour rejection, our data indicate that CD25+FoxP3+ Treg cells only influence the priming phase of the immune response." (PMID 27341421, 2016). "The frequency of CD4 + Foxp3+ regulatory T cells and myeloid-derived suppressor cells (MDSC) was lower in tumor samples from T-VEC- treated patients compared with tumor from non-treated melanoma patients." (PMID 27660707, 2016). "In conclusion, we found that among the three T cell subsets evaluated, only the CD45RO+ T cell density was significantly associated with longer survival in CRC patients, independent of tumor stage, lymphovascular invasion, and CD8+ and FOXP3+ T cell densities." (PMID 25875774, 2015). "Single cell suspensions prepared from spleens, tumours, non-draining lymph nodes (NDLN) and TDLN were analysed by flow cytometry to determine the expression of chemokine receptors by Foxp3+ and Foxp3− T cells." (PMID 25495686, 2015). "Among CD45+ cells, CD8+ T cells and B cells were present at higher frequency in MB49, whereas regulatory CD4+/Foxp3+ cells were more abundant in MB49-I, leading to a very high ratio of cytotoxic to regulatory T lymphocytes in MB49 but not in MB49-I tumours." (PMID 24142880, 2013). "Moroever, there were higher CD8+ TIL densitites in the invasive front than in tumor center (p<0.05), which was not the case for CD3+ and FoxP3+ TIL densities." (PMID 23613769, 2013). "Immunohistochemical examination revealed that the tumour cells expressed T-cell receptor (TCR)-βF1, CD3, CD4, CD25, cytotoxic-related protein TIA1 and granzyme-B, but were negative for CD8, Foxp3, CD20, CD30 and CD56." (PMID 23302373, 2013). "As both tumor size and CD3+ T infiltration are negative prognostic indicators, it is difficult to discern the influence of CD4+ FOXP3+ Treg on tumor progression." (PMID 23060881, 2012). "Under our experimental conditions utilizing BALB/c mice and the RENCA tumor model, TSA (1 mg/kg/day) did not induce changes in either number or Foxp3 expression of Tregs (data not shown)." (PMID 22303460, 2012). "First, a strongly positive correlation was observed between the number of FoxP3+ Tregs and CCL20 expression in tumor tissue (P<0.001), but not in non-tumor tissue (P = 0.894)." (PMID 21935436, 2011). "Even in cases with no obvious PTL inflammation, the higher the number of CD8+, FOXp3+ and CD68+ cells relative to the number of tumor buds (ratio of immune cells-defenders /tumor budding cells-attackers), the more favorable the impact on patient survival." (PMID 21317460, 2010). "Although the presence of CD8+ cells among patients with MSI-H tumors does not seem to influence outcome, the ratio between CD8+, FOXp3+ and CD68+ cells and the presence of tumor budding has an independent effect on prognosis in both MSS and MSI-H cancers." (PMID 21317460, 2010). "Therefore, it may be hypothesised that FOXP3 expression detected in intraepithelial lymphocytes might be ascribed to locally activated CD8+ cytotoxic T cells, particularly in MSI-H CRCs that are characterized by a high density of CD8-positive tumour-infiltrating T cells." (PMID 18985040, 2008).
tumor (continued). "Abundant intraepithelial infiltrations of Treg with very high levels of Foxp3 expression and absence of CCR7 expression were also detected in five primary tumours." (PMID 17262084, 2007). "In addition, there was no significant impairment of Ki67+ tumor cell proliferation nor changes in the tumor infiltration of CD4+, CD8+, FoxP3+ nor Arg1+ cells." (PMID 41226782, 2025). "Within the tumor microenvironment (TME), 4-OI reduced the frequencies of CD8+ and IFNγ+ CD8+ T cells, but had no significant impact on CD4+, Foxp3+ CD4+ T cells, or myeloid-derived suppressor cells (MDSCs), including monocytic (M-MDSC) and granulocytic (M-MDSC) subsets." (PMID 40521193, 2025). "There was a 13.8% increase in immunosuppressive FoxP3+ CD4+ T cells as a total percentage of T cells in KEAP1 KO versus WT tumors; however, we did not detect a difference in the activation state of anti-tumor CD8+ T cells or NK cells." (PMID 41462606, 2025). "This change in hypoxia detected by PAI was correlated with strong positive correlations with CD8+ and CD4+ FoxP3- effector T cell (Teff), and negative correlations with monocyte frequencies, indicating that ITPP promoted more immunogenic tumor microenvironments in both models." (PMID 40594309, 2025). "Thus, our study is the first to indicate a prognostic value of both low FOXP3 TIL count and negative tumour cell PD-L1 expression in the same patient series." (PMID 39883679, 2025). "However, ICB treatment did not affect the infiltration of FOXP3+ Tregs and CD68+ macrophages at any tumor sites (primary tumor and metastases)." (PMID 40591148, 2025). "To evaluate for potential peripheral conversion of Tregs, in a separate experiment, we instead adoptively transferred CD4+Foxp3–GFP– non-Tregs into LLC-bearing B6CD4–/– recipients, which did not demonstrate any conversion to Tregs in the tumor microenvironment." (PMID 40553564, 2025). "Among CD4+ T cells, we noted no changes to the number of tumor-infiltrating FOXP3+ Tregs, and CD4+ FOXP3- effectors in the tumor parenchyma following the combination treatment, suggesting that only CD8+ T cells are critically implicated in the observed phenotype." (PMID 38509063, 2024). "Finally, we analyzed the relationship between TIM‐4 expression and lymphocytes in non‐tumor cells, and the results showed that there was no linear relationship between the proportion of CK‐19−TIM‐4+ cells and CD4+/CD8+/CD4+FOXP3+ cells." (PMID 39235042, 2024). "The IHC assessment of FOXP3+ T cells and CD56+ NK cells showed high heterogeneity in single tumor expression between pathologists; thus, no interpretation and clinical pathological correlation was performed due to a lack of robustness in categorization reporting." (PMID 37190322, 2023). "Therefore, we would like to explore the spatial relationship between CD79A+CD24-PANCK+-BCSCs subpopulation and CD8+ T cells with FOXP3+ or not to reveal the influence of CD79A+CD24-PANCK+-BCSCs subpopulation on CD8+T cells and tumor microenvironment." (PMID 38066053, 2023). "However, the enhanced intratumoral accumulation of Foxp3UP CD8 T cells counteracted the negative effect of FoxP3 overexpression on cytokine production and resulted in a higher number of IFNγ+ TNFα+ CD8 T cells within the tumor." (PMID 36045586, 2023). "Therefore, increased Foxp3/CD8, PD-1/CD4, and PD-1/CD8 ratios and VASH-1 expression in the tumor tissues were considered to suppress anti-tumor immunity more markedly in NEC than in non-NEC components of MiNENs." (PMID 35565281, 2022). "Furthermore, a strong positive correlation (r = 0.783, p < 0.0001) was observed between levels of FoxP3+ Tregs and CD4+LAG-3+ T cells in tumor tissues but not in PBMCs and NILs." (PMID 35455287, 2022).